ATG10 (autophagy related 10)
Diseases named in the same sentence as ATG10 in open-access papers (continued):
Sharing a sentence is not in itself a finding about the gene and the disease.
cancer (continued). "After exclusion criteria were applied, six genes (GBA, ATG10, TRIM27, CD160, ISYNA1, RAD51B) were selected for validating the associations between DNA methylation and BC with MassARRAY EpiTyper assays in validation I (48 sporadic BC cases and 48 matched cancer-free female controls)." (PMID 35812748, 2022). "Moreover, we found that ATG10 is a critical gene in autophagy and cancer." (PMID 31337985, 2019). "Western blot demonstrated that ATG10, PRKCD, and SPP1 were highly expressed in cancer tissues, while IL18RAP and SLC11A1 expression in cancer tissues was lower." (PMID 34631695, 2021). "Considering their biological role, 3 LNM-upregulated genes (ATG10, GATA3 and S100B) are potential markers of aggressive phenotype and increased metastatic potential of cancer cells." (PMID 33658651, 2021). "In Xena, however, ATG10 was found to be non-significantly overexpressed in cancer patients, although KRAS-mut expressed ATG10 more than KRAS-WT patients." (PMID 39057088, 2024). "Although the function of autophagy was complex and often contradictory in cancers, but there were many evidences supporting that upregulation of ATG2B, ATG10, DAPK1 might contribute to good prognosis by promoting autophagy and apoptosis in ES." (PMID 35902797, 2022). "While mutations of autophagy genes (ATGs) are notably rare in cancer, haploinsufficiency network analyses across many cancers have shown that the autophagy pathway is frequently hit by somatic copy number losses of ATGs such as MAP1LC3B/ATG8F (LC3), BECN1/ATG6 (Beclin-1), and ATG10." (PMID 35681458, 2022). "However, the role of ATG10 in cancer has not yet been evaluated." (PMID 23285162, 2012).
infection (7 papers, 2012 to 2023). The state of being infected such as from the introduction of a foreign agent such as serum, vaccine, antigenic substance or organism. "Of particular significance is ATG10, which silencing significantly restored cell viability after infection with two different MRSA strains." (PMID 31659191, 2019). "In addition, we also have assessed the exogenous Atg5-IRGM and exogenous Atg10-IRGM interaction upon CA16 infection." (PMID 25853521, 2015).
bacterial infection (2 papers, 2018 to 2022). "In this study, GO enrichment analysis showed that ATG2 and ATG10 subfamilies play essential roles in response to bacterial infection." (PMID 35055085, 2022). "ATG10 has been shown to play an important role in the invasion and proliferation of cancer cells, and bacterial infections." (PMID 30319633, 2018).
ATG10 also shares sentences with these, for which no sentence is quoted: acute myeloid leukemia (2 papers); inflammatory bowel disease (2); ovarian carcinoma (2); papillary thyroid carcinoma (2); pharyngeal cancer (2); thyroid cancer (2); amyotrophic lateral sclerosis (1); autoimmune disease (1); endometrial cancer (1); frontotemporal lobar degeneration (1); gastric intestinal type adenocarcinoma (1); gastrointestinal stromal tumor (1); major depression (1); myelosuppression (1); neuroblastoma (1); neurodegenerative disease (1); non-small cell lung carcinoma (1); Obesity (1); oral carcinoma (1); palmoplantar pustulosis (1); psoriasis vulgaris (1); rectal cancer (1); rectum adenocarcinoma (1); rheumatoid arthritis (1); tuberculosis (1); type 2 diabetes (1); vascular dementia (1); vasculitis (1); virus infection (1).